TMEM245 (transmembrane protein 245)
Synonyms: C9orf5; CG-2; CG2
Tractability: Antibody: UniProt predicts a signal peptide or a membrane-spanning region; the Human Protein Atlas places it where antibodies can reach. PROTAC: ubiquitination databases record sites on it; its protein half-life has been measured.
Gene: Protein-coding gene on chromosome 9 (109,015,135 to 109,119,974, reverse strand). Ensembl gene ENSG00000106771.
Subcellular location: Membrane
Subcellular location (Human Protein Atlas): Cytosol; Plasma membrane
Gene Ontology:
Cellular component: membrane
Genetic constraint (gnomAD): Loss-of-function variants: 55 observed, 75.42 expected, observed/expected ratio (o/e) 0.73, 90% interval 0.59 to 0.91. The synonymous counts are far from expectation, so gnomAD's model fits this gene poorly and the ratio says little. Missense variants: 960 observed, 906.48 expected, observed/expected ratio (o/e) 1.06, 90% interval 1 to 1.12. Synonymous variants: 498 observed, 374.44 expected, observed/expected ratio (o/e) 1.33, 90% interval 1.24 to 1.43.
Homologues: Orthologues: chimpanzee TMEM245 (99% identical), macaque TMEM245 (98% identical), pig TMEM245 (93% identical), dog TMEM245 (93% identical), rabbit TMEM245 (93% identical), rat Tmem245 (92% identical), mouse Tmem245 (91% identical), guinea pig TMEM245 (88% identical), tropical clawed frog tmem245 (72% identical), zebrafish tmem245 (41% identical), Drosophila melanogaster CG2698 (27% identical), Caenorhabditis elegans M01F1.4 (24% identical).
Diseases named in the same sentence as TMEM245 in open-access papers:
TMEM245 is named in the same sentence as 10 diseases in open-access papers, as found by Europe PMC text mining. Sharing a sentence is not in itself a finding about the gene and the disease. The quoted sentences say what the papers report.
schizophrenia (4 papers, 2013 to 2025). A major psychotic disorder characterized by abnormalities in the perception or expression of reality. "The expression level of TMEM245 has been associated with atrial fibrillation, and schizophrenia-associated variants have been reported within this gene." (PMID 41006818, 2025).
breast carcinoma (1 paper, 2023). "TMEM245 (transmembrane protein 245) is the host gene for microRNA 32, which has been shown to promote proliferation and suppress apoptosis of breast cancer cells." (PMID 36690614, 2023). "Cell-type-specific TWAS using MiXcan identified five genes (ADGRV1, ZNF703, TMEM245, CDYL2, and PSG4), including three novel breast cancer susceptibility genes, that were not identified by either PrediXcan or PredictDB." (PMID 36690614, 2023). "Importantly, MiXcan uniquely identified three novel breast cancer susceptibility genes (ZNF703, TMEM245, and PSG4) that were not previously implicated by breast cancer GWAS11–13 nor TWAS14–16,32." (PMID 36690614, 2023).
Obesity (1 paper, 2025). Accumulation of substantial excess body fat. "While support for other genes identified herein is limited in the literature, SNAPC3, which validated in CCHC, and TMEM245, which generalized to liver tissue, have connections to obesity-related traits." (PMID 41006818, 2025).
TMEM245 also shares sentences with these, for which no sentence is quoted: Alzheimer disease (1 paper); atrial fibrillation (1); depression (1); Familial dysautonomia (1); melanoma (1); prostate carcinoma (1); tumor (1).